IGF1R (insulin like growth factor 1 receptor)
Diseases named in the same sentence as IGF1R in open-access papers (continued):
Sharing a sentence is not in itself a finding about the gene and the disease.
cancer (continued). "Inhibition or removal of IGF-1R blocked the FVIIa-mediated phosphorylation of AKT as well as the protection against TRAIL-induced apoptosis in cancer cells." (PMID 32458278, 2020). "CC cells that are resistant to the EGFR inhibitor erlotinib acquire cancer stem cell (CSC) properties via activation of IGF2/IR/IGF-1R and its downstream signaling to induce EMT." (PMID 32708604, 2020). "First, PQ401 was identified as an inhibitor of IGF-1R that induces the apoptosis of a variety of cancer cells by blocking the autophosphorylation of IGF-1R." (PMID 32605985, 2020). "The initial excitement on the use of anti-IGF-1R antibodies to treat cancers has lived up to the hype in patients." (PMID 33122707, 2020). "Collectively, nuclear IGF-1R exerts transcriptional regulation activity, and its newly discovered role in cancer provides a novel mechanism in IGF1R-mediated cancer progression and can serve as a new biomarker for predicting clinical prognosis." (PMID 33511137, 2020). "Molecularly, high sensitivity of mutant and cancer cells with the OPC feature toward IGF1R targeting likely stems from the intimate coupling between IGF1R and PDGFRα, as the coexpression of both RTKs largely occurs in OPCs in the brain." (PMID 33173731, 2020). "Our results provide lines of evidence that the PSPC1/IGF1R axis is the critical signaling to facilitate cancer cell motility and potentially as a therapeutic biomarker to predict malignant subtypes of cancer for receiving treatments with IGF1R inhibitor." (PMID 32570949, 2020). "It is reported that the underlying anti-cancer mechanisms of NDGA was to inhibit a series of cancer related signaling molecules, such as IGF-1R, HER2, and mTORC1." (PMID 33041789, 2020). "IGF-1R inhibitors have been validated for their efficacy in various cancer types as mono- and combined therapies in preclinical studies." (PMID 32312951, 2020). "Overall, the results from recent studies suggest that nuclear IGF-1R facilitates an aggressive cancer phenotype." (PMID 33584548, 2020). "The rapid endocytosis and subsequent translocation of the IGF-1R to the Golgi in fibroblasts and cancer cell lines requires an adhesion-dependent autophosphorylation on Tyr1250/1251 in the C-terminal tail." (PMID 33584548, 2020). "We identified proteasome inhibitors (MG-132), COX-2 inhibitor (OSU-03012), CASP3 agonists, and an inhibitor of IGF-1R (GSK-1904529A) that targeted genes identified from gene deletion analysis of personalized metabolic networks of cancer samples." (PMID 33396819, 2020). "FoxO1a is a Forkhead box O (FOXO) transcription factor and a downstream target of the IGF-1R/PI3K/Akt pathway implicated in several physiological and pathological processes including cancer." (PMID 32766159, 2020). "In another setting, IGF-1 receptor (IGF-1R) signaling activation in cancer cells in the presence of CAFs expressing IGF-2 induced Oct3/4, Nanog, and Sox2 expression and promoted stemness pathways related to IGF-1R, EMT, PI3K, TGFβ, WNT, and Hedgehog signaling." (PMID 33050580, 2020). "In turn, in cancer cells, IGF1R-, insulin receptor (INSR)- and/or hybrid IGF1R/INSR-independent activity has also been described." (PMID 32977489, 2020). "The insulin-like growth factor-1 receptor is a potent pro-survival tyrosine kinase-containing receptor and is critical for cancer cell survival and participates in tumorigenesis." (PMID 33219221, 2020). "It is downregulated in human cancers, which leads to the upregulation of mTOR and insulin-like growth factor receptor type 1 (IGF1R) in cancer tissue." (PMID 33023154, 2020). "IGF-1R, a receptor tyrosine kinase (RTK), is implicated in the development and progression of malignant tumors." (PMID 32546241, 2020). "The study highlights the potential utility of cixutumumab-ADCs as theranostics against IGF-1R positive cancers." (PMID 33122707, 2020).
cancer (continued). "Since nuclear IGF1R has been linked to an aggressive clinical course and therapy resistance in different types of cancer, much IGF1R related research currently focuses on nuclear IGF1R." (PMID 32701997, 2020). "This suggests, that in migrating normal and cancer cell lines β1-Integrin signaling from the plasma membrane can influence IGF-1R distribution within cells and determine its presence at the Golgi apparatus." (PMID 33584548, 2020). "Insulin-like growth factor-1 receptor (IGF1R) is a tyrosine kinase that is involved in the pathogenesis of many cancers." (PMID 32728182, 2020). "Previous studies have reported that the ratio of IR/IGF-1R expression is important in determining the sensitivity of the cancer cells to the effects of insulin." (PMID 32393319, 2020). "Typical dysregulated pathways in cancer include IGF-1R, PI3K/AKT1/mammalian target of rapamycin (mTOR), mitogen-activated protein kinase (MAPK)/ERK, glycogen synthase kinase-3β (GSK-3β), or Wnt/β-catenin signaling." (PMID 33520985, 2020). "Accordingly, a number of small-molecule RTK inhibitors (RTKIs) and monoclonal antibodies (mAbs) targeting the IGF-binding domain on the IGF1R were developed for use in treating cancer." (PMID 32226608, 2020). "Unsurprisingly, targeting the IGF-1R has been extensively investigated as a strategy in cancer therapy." (PMID 33584548, 2020). "Although numerous efforts were conducted for development of IGF1R inhibitors with promising anticancer effects in preclinical studies, high challenges of unable to prolong life of cancer patients were encountered in multiple clinical trials." (PMID 32570949, 2020). "This work reveals the important role of LA in cancer treatment, thanks to its dual inhibition of the IGF-1R/IR network, which is a serious obstacle to treatment efficacy." (PMID 31988347, 2020). "The IGF-1R is also found in the nucleus of certain cancer cells where it can regulate gene expression." (PMID 33584548, 2020). "IGF-1 signaling plays a role in cancer tumorigenesis and metastasis, which led to the IGF1R becoming a therapeutic target for multiple cancer sites." (PMID 32226608, 2020). "The insulin-like growth factor-1 (IGF-1) binding to the insulin-like growth factor receptor-type 1 (IGF-1R) activates different transduction events, promoting the growth and survival of multiple types of cancer cells." (PMID 32325700, 2020). "For example, efforts to inhibit IGF-1R signaling at the plasma membrane are not very effective, as is evident from the poor success of mAb in targeting the IGF-1R in cancer." (PMID 33584548, 2020). "In fact, the collaborative signaling of IGF1R and integrins via stabilization of IGF1R/integrin cell adhesion complex was reported previously to promote cancer cell growth and motility in multiple cancer types." (PMID 32570949, 2020). "The insulin-like growth factor-1 receptor (IGF-1R) signaling pathway is a well-characterized pathway involved in cancer cell survival and promoting drug resistance." (PMID 32312951, 2020). "IGF-1R, a classical survival signaling, has been shown to regulate stem cell pluripotency, CSCs, or cancer reprogramming." (PMID 33511137, 2020). "Unfortunately, many clinical trials with anti-IGF1R showed only limited responses in small proportions of cancer patients." (PMID 32911852, 2020). "Around the same time, derepression of IRS-1—immediately downstream of IGF-1R—was described as a potent mechanism used by cancer cells to quickly evade single-agent mTORi." (PMID 32630797, 2020). "The IGF-1R is present in the Golgi apparatus of migratory cancer cells where its signaling contributes to aggressive cancer behaviors including cell migration." (PMID 33584548, 2020). "As in the clinical cancers, there was variable IGF-1R expression and we also noted variable AKT phosphorylation, while ERK phosphorylation was detected in all cell lines." (PMID 31857716, 2020).
cancer (continued). "Several key signaling proteins including Ras/MAPK and RTKs, including MET, KIT, VGFR2, EGFR, FGFR and IGF-1R have been demonstrated to locate to the Golgi apparatus, which acts as a signaling hub in normal and cancer cells." (PMID 33584548, 2020). "IGF1R expressed in malignant tumors plays a critical role in cell survival, invasion, metastasis, and angiogenesis." (PMID 32194804, 2020). "IGFs and insulin-induced IGF-1R activation contribute to the progression of cancer and are current chemotherapeutic targets." (PMID 32708604, 2020). "IGF-1 secreted by activated PSCs and fibroblasts in PDAC stroma via IGF-1 receptor (IGF-1R) promote cancer cell migration, invasion and metastasis." (PMID 32660466, 2020). "Numerous studies have shown that IGF-1R is overexpressed in primary tumors and cancer-derived cells." (PMID 33322337, 2020). "IGF-1R or Src mediated cancer cells were correlated with proliferation, differentiation, survival and metastasis, promoting cell-cell signal transduction." (PMID 32340152, 2020). "IGF-1 secreted by activated PSCs and CAFs via sonic hedgehog pathway activates IGF-1R in cancer cells triggering phosphorylation of insulin-receptor or Src substrates to promote PDAC metastasis via intracellular pathways such as RAS/MAPK." (PMID 32660466, 2020). "We confirmed that iBET-151 reduced the expression of RTK mRNA and proteins, including EGFR, ERBB3, MET, and IGF-1R, thereby regulating cancer cell growth and survival." (PMID 33412753, 2020). "Further understanding of IGF1/IGF1R signaling is required to elucidate the significance of IGF1R expression levels in cancer development and malignancy." (PMID 32033461, 2020). "IGF-1R activity can facilitate tumorigenesis, maintenance of the transformed phenotype and cancer progression." (PMID 33584548, 2020). "Based on these new insights, we propose that, through targeting IGF-1R signaling modulation, stem cell therapy and cancer stemness treatment can be further explored." (PMID 33511137, 2020). "IGF-2 also increases insulin receptor/IGF 1 receptor (IGF1R) axis activation in cancer cells to enhance resistance to anti-EGFR-targeted therapy in cholangiocarcinoma." (PMID 33553157, 2020). "Insulin-like growth factor 1 receptor (IGF1R) is a transmembrane receptor tyrosine kinase (RTK) frequently found to be upregulated and associated with cancer progression and patients’ poor prognosis in multiple cancer types including HCC." (PMID 32570949, 2020). "While most cancer cell lines expressed IGF1R at varying levels, the only cell lines which repeatedly showed positive co-immunoprecipitation at basal conditions were HeLa cells and IGF1R-overexpressing MEF cell line cells (R+)." (PMID 32701997, 2020). "Decreased IGF-1 levels reduce rates of malignancy and the inhibition of IGF-1R inhibits cancer growth." (PMID 33291663, 2020). "Although overexpression of IR and IGF-1R in cancer cells recognizes multiple mechanisms, which are reviewed elsewhere, a recently emerged non-mutational mechanism involves the collagen receptor DDR1, which is up-regulated by IIGFs activation and by collagen." (PMID 33364239, 2020). "Further study to clarify the mechanisms behind the effects of this combination should provide a new strategy for cancer chemotherapy using IGF1R inhibitors and also provide insight into the role of IGF1R in M-phase progression." (PMID 32033461, 2020). "Insulin-like growth factor-1 receptor (IGF1R) and other members of the IGF1 receptor pathway have been associated with the development, progression and metastasis of cancer and resistance to anticancer therapies." (PMID 33260481, 2020). "Studies have shown that IGF1R is overexpressed in cancer tissues compared to normal tissues adjacent to the cancer." (PMID 32728182, 2020). "IGF1R is frequently overexpressed in some types of cancer and, in some cases, is required for oncogenic transformation, making it an attractive target for cancer chemotherapy." (PMID 32033461, 2020).
cancer (continued). "KL is a potent regulator of IGF-1R and Wnt/β-catenin signaling, and these pathways are highly relevant for the cancer microenvironment." (PMID 33520985, 2020). "Substantial evidence reveals the role of insulin-like growth factor 1 receptor (IGF1R), a tyrosine kinase receptor which transmits signals to support cell proliferation, differentiation, survival and metabolism in most types of cancer." (PMID 32549375, 2020). "In TNBCs, stromal CAFs were identified as the source of IGF-1 and CXCL12, which were shown to prime cells to home the CXCL12- and the IGF1-rich bone microenvironment, in a process dependent on CXCR4 and IGF-1R expression by cancer cells." (PMID 33364239, 2020). "In this review, we examine IGF-1R downregulation and endocytosis as related to the rise and fall of IGF-1R targeted cancer therapy." (PMID 31600876, 2019). "The Src/ERK/Egr-1 signaling pathway is the most typical downstream pathway of IGF-1/IGF-1R, which participates in various physiological processes of cells as well as the occurrence and development of various cancers." (PMID 31661546, 2019). "By interacting with both IGF-1R and the intronic DNA enhancer (by intrachromosomal loop), IRAIN is preventing cancer development through declined IGF-1R expression." (PMID 31847392, 2019). "The insulin receptor (IR) and the IGF-1R, prevalently dysregulated signaling pathways in cancer and DM, have been reported to regulate or be regulated at different levels by ncRNAs." (PMID 31847392, 2019). "TGFBRI and IGF1R can participate in the regulation of cell proliferation, differentiation, invasion and migration of cancer cells." (PMID 31035970, 2019). "Since the insulin-like growth factor receptor (IGF-1R) is overexpressed in different cancer cells and the IGF-1-dependent pathway plays a major role in cancer cell proliferation, novel approaches aim to inhibit IGF-1R in cancer treatment." (PMID 31284426, 2019). "IGF1R is expressed in a variety of cancers and blocking IGF1R expression enhances apoptosis and suppresses metastasis in pancreatic cancer cells." (PMID 30809507, 2019). "As such, the IGF system has emerged as an obvious target for cancer therapy, fueling development of several anti-IGF-1R drugs and subsequent clinical trials." (PMID 31600876, 2019). "IGF1R signaling is also responsible for the maintenance of the transformed phenotype by modulating cancer cell motility, adhesion and angiogenesis." (PMID 30929166, 2019). "Although numerous in vitro and in vivo studies have proven that the strategy is feasible in the treatment of DM as well as in cancer, there are still challenging issues that need to be addressed for targeting the IGF-1R, especially in clinical settings." (PMID 31847392, 2019). "Due to the ability of IGFs to bind potently to IGF-1R and activate pathways associated with cellular proliferation, the IGF: IGF-1R interaction has long been recognized for its contribution to cancer growth and propensity for metastasis." (PMID 31416218, 2019). "IGF1R plasmids were transfected in allogeneic HER2/neu-positive IL12-producing murine cancer cells to obtain adjuvanted cell vaccines co-expressing HER2/neu and IGF1R." (PMID 30979001, 2019). "IGF-1R, a transmembrane heterotetrameric protein, can promote cancer cell proliferation, survival and transformation toward malignancy." (PMID 31217907, 2019). "This is important as dysregulated IGFBP5 transcriptional control can act as a driver of cancer growth and metastasis, regulating cell proliferation, differentiation and metabolism using both IGF1R-dependent as well as -independent mechanisms of action." (PMID 31881017, 2019). "IGF1R appears to represent an ideal therapeutic target in many cancers; it is expressed on the cell surface, possesses enzymatic activity and has a role in many tumourigenic processes." (PMID 31179642, 2019). "It has been reported that, IGF1R induces drug-resistivity of Huh7 against anti-cancer agent, through inhibition of caspase-3." (PMID 30944375, 2019).
cancer (continued). "Extensive experimental and epidemiological studies have thoroughly documented the link between malignancy and IGF-1R across the majority of human cancer types." (PMID 31600876, 2019). "Two disease areas in particular are the focus of active investigation, to explore the potential of IGF-1R inhibition for non-cancer indications." (PMID 31416218, 2019). "IGF1R plays a role in the growth of different cancer types and immune targeting by specific antibodies or inhibitors has been studied at a clinical level, with limited activity." (PMID 30979001, 2019). "IGF-1R signaling also has crosstalk with molecules involved in inflammation, which is also a common biological process of DM and cancer." (PMID 31847392, 2019). "Accordingly, studies on the inhibition of IGF-1R expression by siRNA in various cancer cells have been indicated that IGF1-R silencing significantly decreases tumorigenicity and metastasis." (PMID 30041514, 2019). "IGF1R has tyrosine kinase activity, which plays a significant role during cancer cell transformation mainly via cytoprotection and anti-apoptosis." (PMID 30642292, 2019). "IGF-1R is a ubiquitous growth receptor, which is involved in the regulation of proliferation, apoptosis, differentiation, and malignant transformation of cancer cells." (PMID 31467485, 2019). "In agreement with the well-documented finding that the IGF1R gene is overexpressed in most types of cancer, IGF1R levels (both total and phosphorylated) have been found to be drastically reduced in LS cells." (PMID 31208077, 2019). "For example, in a pancreatic ductal adenocarcinoma model, IGF-1R tyrosine kinase inhibitor, linsitinib, eliminated residual dormant cancer cells with ablation of K-RAS or c-MYC oncogenes." (PMID 31505803, 2019). "Past studies reported that CC, breast and livers cancers exhibits high level of IGF-1R overexpression." (PMID 30705329, 2019). "Over the last few decades, the potential of IGF-1R as a target for cancer treatment has been extensively investigated and almost exclusively aligned to the kinase-fits-all model." (PMID 31600876, 2019). "Most of the studies have tried to explore the effect of IGF-1R inhibition to elucidate the possible use of IGF-1R as a target in cancer treatment." (PMID 31467485, 2019). "Targeting IGF-1R is a therapeutic strategy for cancer, up regulation of miR-497 slowed pancreatic cancer progression and increased the sensitivity to gemcitabine." (PMID 31847392, 2019). "IGF1R signalling appears to be required for epithelial‐to‐mesenchyme transition in some cancer cells, driving malignant progression." (PMID 31179642, 2019). "The loss of functional E‐cadherin would impair the adherens junction formation, and release IGF1R to re‐localize to the entirety of the cell membrane where the IGF1 ligand is easily bound for initiating cancer signaling." (PMID 30977227, 2019). "The central roles in cancer of RTKs in general and IGF-1R in particular have been known for many decades, and they serve as targets for many therapeutic approaches." (PMID 31600876, 2019). "Highly engineered cancer cells were the most powerful immunogen in the induction of anti-IGF1R antibodies, as well as in the induction of anti-HER2 antibodies in several other systems, including humanized mice." (PMID 30979001, 2019). "Functional cross-talk of MET with other RTKs, such as EGFR, HER2, HER3, RET or IGF1R, was identified in various cancers as mediating inhibitors resistance." (PMID 31040922, 2019). "This concept, fundamentally true for all anti-IGF-1R strategies, emerged from the early antisense-based experimental work, which described complete inhibition of cancer cells growing in monolayer or as xenografts in animal models." (PMID 31600876, 2019). "In the context of cancer, the IGF1R exhibits important features that are critical for the cellular events associated with the tumorigenic process." (PMID 29455671, 2018).